CA4 (carbonic anhydrase 4)
Description:
Catalyzes the reversible hydration of carbon dioxide into bicarbonate and protons and thus is essential to maintaining intracellular and extracellular pH. May stimulate the sodium/bicarbonate transporter activity of SLC4A4 that acts in pH homeostasis. It is essential for acid overload removal from the retina and retina epithelium, and acid release in the choriocapillaris in the choroid.
Synonyms: CAIV; Car4; RP17
Tractability: Small molecule: an approved drug acts on it; a structure with a bound ligand is known; a high-quality ligand is known; it belongs to a druggable protein family. Antibody: UniProt places it where antibodies can reach, with high confidence; its Gene Ontology location is reachable by antibodies, with high confidence; UniProt predicts a signal peptide or a membrane-spanning region. PROTAC: a small molecule that binds it is known.
Target class: Enzyme; Lyase
Chemical probes: SPERMINE
Gene: Protein-coding gene on chromosome 17 (60,147,838 to 60,170,899, forward strand). Ensembl gene ENSG00000167434.
Subcellular location: Cell membrane
Subcellular location (Human Protein Atlas): Cytosol; Vesicles
Pathways (Reactome):
Transport of small molecules: Erythrocytes take up carbon dioxide and release oxygen; Erythrocytes take up oxygen and release carbon dioxide
Metabolism: Reversible hydration of carbon dioxide
Gene Ontology:
Molecular function: carbonate dehydratase activity; protein binding; zinc ion binding
Biological process: bicarbonate transport
Cellular component: apical plasma membrane; basolateral plasma membrane; brush border membrane; cell surface; endoplasmic reticulum-Golgi intermediate compartment; external side of plasma membrane; extracellular exosome; Golgi apparatus; perinuclear region of cytoplasm; plasma membrane; rough endoplasmic reticulum; secretory granule membrane; trans-Golgi network; transport vesicle membrane; membrane
Genetic constraint (gnomAD): Loss-of-function variants: 25 observed, 35.81 expected, observed/expected ratio (o/e) 0.7, 90% interval 0.51 to 0.98. The upper end of that interval is the gene's LOEUF score, 0.98, which puts it in group 4 of 6, group 1 being the genes least tolerant of losing a copy. Missense variants: 394 observed, 401.54 expected, observed/expected ratio (o/e) 0.98, 90% interval 0.9 to 1.07. Synonymous variants: 178 observed, 170.28 expected, observed/expected ratio (o/e) 1.05, 90% interval 0.92 to 1.18.
Homologues: Orthologues: chimpanzee CA4 (99% identical), macaque CA4 (86% identical), pig CA4 (70% identical), guinea pig CA4 (63% identical), rat Car4 (58% identical), rabbit CA4 (57% identical), mouse Car4 (56% identical), zebrafish ca4a (39% identical), zebrafish ca4b (37% identical), tropical clawed frog ca4.2 (36% identical), zebrafish ca4c (35% identical), tropical clawed frog ca4.2 (31% identical), and 9 more. Paralogues in human: CA14 (31% identical), CA12 (31% identical), CA6 (29% identical), CA9 (29% identical), CA2 (27% identical), CA7 (27% identical), CA5A (26% identical), CA5B (26% identical), CA13 (26% identical), CA8 (25% identical), CA3 (25% identical), CA1 (24% identical), and 2 more.
Diseases named in the same sentence as CA4 in open-access papers:
CA4 is named in the same sentence as 126 diseases in open-access papers, as found by Europe PMC text mining. Sharing a sentence is not in itself a finding about the gene and the disease. The quoted sentences say what the papers report.
breast carcinoma (20 papers, 2016 to 2025). "M138 signifies a unique capillary endothelial subset characterized by CA4 overexpression, and its presence is robustly predictive of a good prognosis in breast cancer." (PMID 41066207, 2025). "M138 signifies a unique capillary endothelial subset characterized by CA4 over-expressions, and its presence is robustly predictive of good prognosis in breast cancer." (PMID 39764102, 2024). "Notable exceptions to this pattern are CA4, which is detected only in breast cancer endothelial cells, and CA7, which is expressed exclusively in cancer-associated fibroblasts and myeloid cells." (PMID 37098526, 2023). "Most markedly CA9/Car9 and CA12/Car12 are upregulated, whereas CA4/Car4 is downregulated in human as well as murine breast cancer tissue." (PMID 37098526, 2023). "Apart from ZLM-7, 2-Methoxy-5 ((3,4,5-trimethosyphenyl) seleninyl) phenol (SQ) is another synthesized structural analogue of CA-4 with a proven cell-cycle blocking effect that has been investigated to be a potential treatment for breast cancer." (PMID 35890172, 2022). "We have previously reported the synthesis of a series of CA-4 analogues with structures based on the conformationally constrained 2-azetidinone ring, demonstrating potent activity in breast cancer cells." (PMID 33671674, 2021). "Cytotoxicity of free CA-4 and novel PEGylated poly(α-lipoic acid) graft CA-4 nanoparticles was measured with MTT test through 4T1 breast cancer cell line." (PMID 32486408, 2020). "For example, the allosteric mTOR inhibitor temsirolimus significantly enhanced the anti-cancer activity of CA4-nanoparticles in a breast cancer model." (PMID 31888052, 2019). "CA-4 had been previously proposed to be a potential agent for the treatment of breast cancer." (PMID 35890172, 2022). "They concluded the CA-4 loaded APRPG-PEG-PDLLA/MPEG-PDLLA mixed micelles might be a new strategy for breast cancer therapy and could also be a potential carrier." (PMID 32486408, 2020). "Decreased CA4 mRNA expressions were found in datasets of brain and CNS cancer, breast cancer, colorectal cancer, gastric cancer, head and neck cancer, kidney cancer, leukemia cancer, lung cancer, pancreatic cancer and sarcoma compared to normal tissues from Oncomine database." (PMID 32922550, 2020). "In addition, CA4 also induced significant tumor growth inhibition in the mouse model bearing human breast cancer." (PMID 27338725, 2016). "Combretastatins CA-4 4a, (phosphate prodrug 4b), CA-1 4c (phosphate prodrug 4d), 4e, and serine prodrug ombrabulin 4f have demonstrated impressive antiproliferative potency with microtubule destabilising and anti-vascular effects in many cancers, including breast cancer." (PMID 33671674, 2021). "Based on proteomic data from human biopsies, we additionally confirm the expression of cytosolic (CA1, CA2, CA3, CA13), mitochondrial (CA5β), and extracellular (CA4, CA6, CA9, CA12) carbonic anhydrases in breast cancer tissue." (PMID 37098526, 2023). "These morphological changes are similar to those observed for the CA4 mechanism and were also observed with the KGP18-treated MDA-MB-231 breast cancer cells." (PMID 34638255, 2021). "These morphological changes were similar to those observed with CA4 and OXi8006 and were also observed with KGP18-treated MDA-MB-231 breast cancer cells." (PMID 34638255, 2021). "In summary, these novel 3-vinyl-β-lactam analogues of CA-4 which we now report show potent antiproliferative effects in preliminary in vitro investigations on MCF-7 and MDA-MB231 breast cancer cells." (PMID 30979033, 2019). "In in vivo assay, CA4 suppressed neovascularization in chicken chorioallantoic membrane (CAM) model and decreased the microvessel density in tumor tissues of a breast cancer MCF-7 xenograft mouse model." (PMID 27338725, 2016).
breast carcinoma (continued). "Breast cancer MCF7 cells treated with compound 42 for 72 h were mostly classified as live cells (88%), whereas lower percentages of live cells were found when treated with compounds 38 (60%), 45 (71%) and the reference compound CA-4 (58%)." (PMID 33673002, 2021). "Similarly with the previous studies, cis-stilbenes were more potent than the other groups of compounds, against A-549 lung carcinoma, MCF-7 breast carcinoma, HT-29 colon adenocarcinoma, SKMEL-5 melanoma, and MLM melanoma cell lines, though being a 20 times less potent than CA-4." (PMID 32486408, 2020). "Finally, 6 upregulated DEGs (CST2, DRP2, CLEC5A, SCD, KIAA1211, DTL) and 6 downregulated DEGs (STAC2, BTNL9, CA4, CD300LG, GPIHBP1 and PIGR), were confirmed in a quantitative real time PCR comparison of breast cancer and paracancerous breast tissues from 8 clinical specimens." (PMID 31182966, 2019).
colon carcinoma (13 papers, 2008 to 2025). "However, downregulation of CA4 is mainly associated with tumors and cancers, such as colon cancer." (PMID 37978561, 2023). "For example, the tumour suppressor carbonic anhydrase IV (CA4) inhibits colon cancer development by targeting the WTAP-WT1-TBL1 axis to inhibit Wnt signaling." (PMID 35143566, 2022). "Despite CA-4’s potency in many cancer cell lines, it is ineffective against HT-29 colon cancer cells." (PMID 31947889, 2020). "MTT assays already revealed some CA-4 characteristics such as selectivity for EA.Hy926 endothelial hybrid cells and a reduced efficacy against HT-29 colon carcinoma cells." (PMID 30658435, 2019). "Most significantly, KSS19 was able to overcome CA4 resistance in colon cancer subtypes exemplified by HT29 cells which express higher levels of the COX-2 enzyme." (PMID 29899846, 2018). "In addition, WTAP was essential for the tumor-suppressor function of carbonic anhydrase 4 (CA4) in colon cancer." (PMID 36171885, 2022). "Hence, CA-4’s B ring may provide fertile grounds for activity optimization of novel analogues for the treatment of MDR colon cancers." (PMID 31947889, 2020). "CA4 is a tumour suppressor gene for colon cancer that inhibits the Wnt pathway by attenuating WTAP–WT1–TBL1 axis, among which WTAP is degraded because CA4 is stimulating its polyubiquitination." (PMID 32998774, 2020). "KSS-19 showed potent anti-proliferative activity against a panel of colon cancer cell lines; HT29 cells, which are resistant to CA4 were 100 times more sensitive to KSS19." (PMID 29899846, 2018). "We thus provide mechanistic insights which may explain an earlier study where low dose CA-4 application (2 mg/kg) in a rat model of intrahepatic colon carcinoma acted synergistically with anti-cancer immunization without changing the tumor’s vascular density." (PMID 40140727, 2025). "Furthermore, WTAP interacts with carbonic anhydrase IV (CA4) to induce WTAP protein degradation through polyubiquitination, which may inhibit colon cancer development by suppressing the Wnt signaling pathway." (PMID 40986143, 2025).
colorectal cancer (9 papers, 2016 to 2025). A primary or metastatic malignant neoplasm that affects the colon or rectum. "The prognosis of LUAD, KIRC and LGG patients with low expression of CA4 is poor, which is consistent with the findings in colorectal cancer and renal cell carcinoma." (PMID 33195408, 2020). "The one cell line that was only minimally affected by treatment with CA4 was the HT-29 colorectal cancer cell line, which had been previously established as CA4-resistent." (PMID 28253265, 2017). "CA4 was found to have potent anti-proliferative activity in an osteocarcoma cell line (MG-63) and one of two colorectal cancer cell lines (HCT-116, HT-29)." (PMID 28253265, 2017). "Recent study firstly stated that CA4 was a tumor suppressor in colorectal cancer (CRC) by inhibiting the Wnt signaling pathway." (PMID 29340021, 2017). "Carbonic anhydrase IV (CA4) is silenced in colorectal cancer (CRC)." (PMID 36207306, 2022). "Herein, we analyzed a series of synthetic CA-4 analogs featuring N-methylimidazole-bridged Z-alkenes with different halo- or amino-substituted aryl rings in vitro and in vivo, focusing on models of colorectal cancer." (PMID 34884888, 2021). "In addition, the regulating or inhibiting factors of m6A modifications may act as potential strategies for cancer treatments, as observed for MA2 in glioblastoma multiforme, R-2HG/SPI1/FB23-2 in acute myeloid leukemia, and CA4 in colorectal cancer." (PMID 33791305, 2021).
glioma (8 papers, 2016 to 2023). A benign or malignant brain and spinal cord tumor that arises from glial cells (astrocytes, oligodendrocytes, ependymal cells). "CA4P, a water-soluble prodrug of CA4, is used as a vascular-disrupting agent for the treatment of ovarian, glioma, non-small cell lung cancer (NSCLC), pancreatic neuroendocrine tumors, and etc.." (PMID 32265711, 2020). "Since we found that CTX and CA4 are effective in blocking endothelial tube formation and since these vascular challenges are presumably important for glioma growth, we wanted to prove this anti-angiogenic activity in a complex brain tumor microenvironment." (PMID 26831010, 2016). "We hypothesize that nanoformulation of CA4 may represent an improved approach to target tumor vasculature of glioma." (PMID 30656065, 2018). "Interestingly, CTX and CA4 were both effective on freshly isolated primary glioma cells and showed a 30% to 40% reducing effect on cell growth at maximal concentration." (PMID 26831010, 2016). "In addition, CA4 appears to be highly efficacious in inhibiting glioma functions such as growth, membrane extensions and filopodia motility and migration." (PMID 26831010, 2016). "Both CA4 and CTX-23 peptides inhibit rodent and human glioma cell growth already at low concentrations." (PMID 26831010, 2016). "In our assays we found that CA4 and CTX-23 were equally effective in reducing glioma cell growth as CTX." (PMID 26831010, 2016). "Altogether, these results demonstrate that CA4, CTX-23 and CTX act as migratory inhibitors with CA4 revealing the strongest motility inhibitor on various glioma cell species." (PMID 26831010, 2016). "In contrast, delivery of CA4 alone has no therapeutic effect in an experimental rat model of glioma." (PMID 30656065, 2018). "Although CA4 can cause necrosis in the tumor core of various types of solid tumors, in gliomas CA4 alone does not effectively induce a central necrosis." (PMID 30656065, 2018). "The novel peptides CA4 and CTX-23 are both effective in reducing glioma cell proliferation." (PMID 26831010, 2016). "The construct without CA4 conjugation had no therapeutic effect on glioma whereas, CA4 conjugated nanocombretastatin showed significant blood flow decrease in an experimental rat model of glioma." (PMID 30656065, 2018).
lung carcinoma (6 papers, 2018 to 2025). "It has been reported in previous literature that NEK2, TOP2A, PLK1, CA4, and AURKB can play oncogenic or tumor suppressing roles in the progression of lung cancer." (PMID 35646063, 2022).
retinitis pigmentosa (6 papers, 2013 to 2024). Retinitis pigmentosa (RP) is an inherited retinal dystrophy leading to progressive loss of the photoreceptors and retinal pigment epithelium and resulting in blindness usually after several decades. "Patient two had a clinical diagnosis of retinitis pigmentosa and the Invitae kit reported BBS10, CA4, and NPHP1 as VUS; BG reported RCBTB1 and CA4 as VUS." (PMID 38892829, 2024).
glioblastoma (5 papers, 2016 to 2025). The most malignant astrocytic tumor (WHO grade IV). "Studies surrounding glioblastoma multiforme are being investigated, with CA-4 being one of the new agents being considered." (PMID 40032960, 2025). "Further we investigated whether CA4 is also acting on primary glioblastoma cells from human specimens in comparison to CTX." (PMID 26831010, 2016).
viral infection (5 papers, 2020 to 2025). "The fact that ATP-to-ITP conversion is only observed upon cA4 or cA6 binding suggests an allosteric regulation of ATP binding by the second messenger produced upon viral infection." (PMID 41107544, 2025). "The KEGG analysis revealed that the upregulated genes in Ca4-low ECs were significantly enriched in viral infections, bacterial infections, and cellular processes such as apoptosis." (PMID 38552230, 2024). "These are all examples where two effectors, each activated the same cA4 species, are present in one locus and presumably provide broad defence by targeting two different biomolecules simultaneously to slow down viral infection." (PMID 38808661, 2024). "The Crn1 family of ring nucleases, based on the CARF domain fold, was originally identified in the Sulfolobales and related crenarchaea, where their function is thought to be to remove cA4 from the cell once a viral infection has been cleared." (PMID 32597755, 2020).
lung adenocarcinoma (4 papers, 2018 to 2023). A carcinoma that arises from the lung and is characterized by the presence of malignant glandular epithelial cells. "CA4 and HMOX1 achieved the best AUC performance (AUC = 0.9 and AUC = 0.89) in liver hepatocellular carcinoma, LTC4S and NEUROD1 in lung adenocarcinoma (AUC = 0.998 and AUC = 0.994), FANCA and ARG2 in lung squamous cell carcinoma (AUC = 0.992 and AUC = 0.956)." (PMID 29304754, 2018). "In addition, some potential target genes of the quercetin, such as TOP2A, CA4 and AURKB were related to the prognosis of lung adenocarcinoma patients." (PMID 36949111, 2023).
ovarian carcinoma (4 papers, 2014 to 2024). A malignant neoplasm originating from the surface ovarian epithelium. "Because high β-galactosidase activity is reported in not only ovarian cancer but also in other malignant tumors, CA4-βGAL-2 can also be used as a prodrug candidate for PMT for these malignant tumors." (PMID 38543094, 2024). "Corroborating these data, a CA4 analogue called 8A, which showed increased antimitotic activity, caused apoptosis in HCT-116, SMMC-7221 liver cancer and A2780 ovarian cancer cell lines." (PMID 37111767, 2023). "In our efforts to discover cytotoxic agents against ovarian cancer cells, a series of CA-4 related compounds were synthesized and evaluated for their anti-proliferative activities in human epithelial ovarian cancer cell line A2780 in vitro (data not shown)." (PMID 25180593, 2014). "CA4-βGAL-2 exhibited more potent cytotoxicity to ovarian cancer cell lines than CA4-βGAL-1." (PMID 38543094, 2024).
COVID-19 (3 papers, 2021 to 2024). A disease caused by infection with severe acute respiratory syndrome coronavirus 2. "We assume that CA4 on blood cells can act likely in the acidotic status resulting from hypoxia created by COVID-19." (PMID 34457122, 2021). "Corresponding proteins from many of these DEGs have already been identified as drug targets for the treatment of various diseases such as COVID-19, asthma or rheumatoid arthritis (e.g., CCR2, CCR3, CXCL8, JAK3, HRH, CA4, see clinicaltrials.gov)." (PMID 38242945, 2024).
leukemia (3 papers, 2017 to 2024). A malignant (clonal) hematologic disorder, involving hematopoietic stem cells and characterized by the presence of primitive or atypical myeloid or lymphoid cells in the bone marrow and the blood. "RO-3306 could prevent CA4-linked mitochondrial depolarisation in both leukemia models tested, although the protective effect was only significant in the E6-1 cell line." (PMID 28253265, 2017). "In addition, RO-3306 could prevent a decrease in cell viability normally associated with CA4 treatment, in the E6-1 leukemia cell line." (PMID 28253265, 2017). "CA4 has been shown to be cytotoxic towards some cancer cell lines such as the leukemia cell line, P-388, which is resistant to daunorubicin." (PMID 36865913, 2023). "In MV-4-11 leukemia cells, co-incubation of reversine with CA4 and analogues concomitantly prevented mitotic arrest, as evidenced by cyclin B1 western blotting, and mitochondrial depolarisation, which suggested a causal connection." (PMID 28253265, 2017). "However, one study showed lower selectivity, with CA-4 exhibiting antiproliferative effects on human lymphocytes, although it still exhibited significantly higher cytotoxicity for HL-60 (human leukemia) and OVCAR-8 (ovarian adenocarcinoma) tumor cell lines." (PMID 39766242, 2024).
triple-negative breast carcinoma (3 papers, 2023 to 2025). An invasive breast carcinoma which is negative for expression of estrogen receptor (ER), progesterone receptor (PR), and human epidermal growth factor receptor 2 (HER2). "These compounds were also potent in the triple-negative breast cancer (TBNC) cell line MDA-MB-231, with IC50 values in the range 23–33 nM, and were comparable with the activity of CA-4." (PMID 37513912, 2023).